AXL (AXL receptor tyrosine kinase)
Diseases named in the same sentence as AXL in open-access papers (continued):
Sharing a sentence is not in itself a finding about the gene and the disease.
tumor (continued). "However, there was markedly elevated expression of both AXL and CDCP1 in recurrent tumor after treatment with osimertinib." (PMID 35643725, 2022). "AXL is one of the TAM (Tyro3/Axl/Mer) receptor families, the intracellular segment of AXL has kinase activity and can participate in the transmission of various signaling pathways in normal cells and tumor cells." (PMID 36408274, 2022). "Regardless of the overall AXL expression levels, the protein was found to be heterogeneously expressed, showing positive staining in both the tumor periphery and its central areas." (PMID 35332208, 2022). "Further analysis indicated that AXL inhibition upregulated expression of PD-L1 and MHC I (on murine tumor cells) and PD-1 (on T cell populations) and that AXL inhibition, using bemcentinib or SGI-7079, combined with PD-1 blockade resulted in cure of ID8 and 4T1 tumor-bearing mice." (PMID 35572601, 2022). "AXL inhibition in tumor cells decreases the secretion of pro-angiogenic factors such as endothelin and VEGF-A and impairs functional properties of endothelial cells in vivo, suggesting its important role in the initiation of tumor angiogenesis." (PMID 35813203, 2022). "In addition, a recent combination strategy of AXL-CAR-T plus constitutive active IL-7 receptor blockade exhibited strong cytotoxic effects in vitro and reduced tumor size in MDA-MB-231-derived xenograft mouse models." (PMID 35414783, 2022). "IGF1 and GAS6 can then reciprocally affect tumor cells, via the IGF1R/AXL-AKT axis." (PMID 36612058, 2022). "Moreover, moderate antitumour efficacy of AXL-CAR T cells was observed in both subcutaneous and lung metastatic CDX tumour models in vivo." (PMID 36261437, 2022). "However, immunohistochemistry revealed that AXL inhibition reduced the number of Foxp3+ Tregs (cells/mm2) that infiltrated tumor tissues in both the TC1 and C3PQ tumor models (*p<0.05)." (PMID 35356198, 2022). "Interestingly, the investigators noted variations in AXL and MERTK expression during tumor progression and treatment exposure." (PMID 35572601, 2022). "It is thus tempting to speculate that an RTK spectrum beyond ERBB3, EGFR, and AXL might be affected by SLC35B2 levels, depending on individual tumor type and treatment context." (PMID 35798875, 2022). "Although AXL was not statistically significant, there was a trend of high expression in tumor tissue." (PMID 36105100, 2022). "To investigate whether MWA could enhance the tumour-suppressive properties of AXL-CAR T cells in NSCLC, we constructed an AXL-positive NSCLC PDX (patient-derived xenografts) tumour model for an in vivo combination study to mimic the primitive TME of NSCLC." (PMID 36261437, 2022). "In addition, AXL-targeted CAR T cells showed killing effects in breast cancer models in vivo and various tumour models in vitro." (PMID 36261437, 2022). "In present study, we found that AXL was mainly expressed in the TECs but not in the tumor cells of HCC patients." (PMID 34123800, 2021). "Forced expression of an active form of AXL, but not a kinase-impaired AXL, in erlotinib-sensitive tumor cells was sufficient to induce erlotinib resistance." (PMID 34830794, 2021). "Strong AXL expression was observed on the surface of cancer cells and in tumor stroma (data not shown)." (PMID 34877810, 2021). "AXL is a member of the TAM family, and it transduces signal through the high-affinity ligand growth arrest-specific protein 6 (GAS6), thereby driving the proliferation, migration and invasion of tumour cells." (PMID 34335945, 2021). "In addition, MERTK expression was increased when NSCLC cell lines were treated with AXL inhibitor or AXL expression was inhibited using siRNA and dual inhibition of AXL and MERTK reduced cell expansion in vitro and tumor growth in vivo." (PMID 34830794, 2021). "The expression of an indicated mRNA in the AXL-positive cells was calculated relative to its expression in AXL-negative cells from the respective tumor." (PMID 34254585, 2021).
tumor (continued). "Quantitative RT-PCR analysis of 8 tumor xenograft-derived cell lines showed that none had lost expression of either GAS6 or AXL; in fact, 6 of 8 had acquired significantly increased expression of MERTK (also activated by Gas6) and KDR." (PMID 34292953, 2021). "However, tumor-infiltrating CD8+ T and CD4+ T cells subjected to AXL inhibition showed a noticeable induction of PD-1 on their surface." (PMID 34778071, 2021). "Erlotinib could stimulate tumor cell to produce resistance by alternative pathways such as MET, HER2, or AXL pathway." (PMID 34368128, 2021). "In sharp contrast, we detected no tumor formation in any of the four animals injected with AXL knock-out AXL-c17 cells after 10 weeks of follow-up (p = 0.0042)." (PMID 34948046, 2021). "AXL overexpression in HUVECs promoted tumor growth and liver or vessel metastasis of HCC in xenograft nude mice, which could be counteracted by treatment with R428, an AXL inhibitor." (PMID 34123800, 2021). "Accompanying this were significant changes in regulators of inflammation that were consistent with a shift from AXL to MERTK signaling, which have been distinguished in carefully controlled studies that refine our understanding of TAM receptor signaling in tumor immune surveillance." (PMID 34292953, 2021). "Extracellular domains of MERTK and AXL fused to the Fc domain of immunoglobulin G1 can also titrate GAS6 and thereby block GAS6-dependent signaling through the TAM kinases, resulting in decreased tumor metastasis." (PMID 34830794, 2021). "Treatment with anti-AXL antibody inhibits AXL-dependent EMT and tumor growth in TNBC patients." (PMID 33805447, 2021). "Within a tumor, not all the tumor cells expressed AXL, showing intra-tumor heterogeneity of AXL staining." (PMID 31963783, 2020). "Moreover, AXL physically interacts with proteins, such as FLT3, FGFR, and TYRO3, to accelerate tumor cell migration and invasion." (PMID 32346605, 2020). "Our results showed that AXL-CAR.C7R cell-treated mice showed no inhibition in tumor growth when compared with the PBS group." (PMID 31998790, 2020). "In addition to engineered recombinant cell lines, the ability of INCB081776 to modulate AXL and MERTK activity was evaluated in tumor cell lines expressing high levels of endogenous AXL or MERTK." (PMID 33425754, 2020). "For AXL-specific or TYRO3-specific inhibitors, the desired anti-tumor immunological effect could be relatively easy to reach as these receptors dominantly function as immune-inhibitory receptors on APCs." (PMID 31664482, 2020). "Therefore, we detected the expression of hypoxia-inducible factor 1α (HIF-1α), tyrosine-protein kinase receptor UFO (AXL) mRNA, and vascular endothelial growth factor (VEGF) mRNA to observe the effect of TNuF on the angiogenic pathway in tumor cells." (PMID 32872195, 2020). "Besides, ABCB5 was critical to tumor vascular invasion and the ABCB5-dependent metastatic propensity was found to be dependent on IL-8/AXL signaling." (PMID 32357409, 2020). "Expression of AXL in the cell cytoplasm of pre-EGFR-TKI-treated tumor samples was evaluated using immunohistochemistry (IHC) staining and scored as very high (3+), high (2+), low (1+), and no expression of AXL." (PMID 32929081, 2020). "To assess the nonspecific cytotoxicity of AXL-CAR-T cells, we established mouse models with AXL-negative MCF-7 xenograft tumor as controls." (PMID 31998790, 2020). "In our LATS1/2 cKO mouse model, although some of the tumour markers were highly present in the centre of the tumour mass, e.g., ANKRD1, Vimentin, CK18, nestin and Ki67, some were localised towards the edges of the tumour, e.g., HOPX, AMOTL2, AXL and microglial marker C3." (PMID 32404936, 2020). "AXL inhibition by BGB324 may, thus, represent a promising concept with anti-fibrotic, immune-stimulatory, and also anti-tumour effects." (PMID 31822557, 2020).
tumor (continued). "The AXL-high clone produced larger tumours more rapidly than the bulk H1299 cells, whereas the AXL-low clone developed no tumours at 12 injection sites in six mice by day 35 of the experiment." (PMID 32051483, 2020). "In AXL–/–/HER2+ mouse tumor models, a decrease in EGF, Rho-GTPase, and TGF-β (transforming growth factor β) signaling is observed compared to in AXL-competent cells, indicating that AXL promotes signaling through these pathways." (PMID 32148495, 2020). "In contrast, CYR61 and AXL levels were not increased in +DDR1/+COL1 tumours when compared to −DDR1/+COL1 tumours." (PMID 32047176, 2020). "These in vivo studies showed that although no heterogeneous expression of AXL was found in the tumor mass, it was still greater in tumor cells near the stroma." (PMID 33182542, 2020). "Merestinib is a potent inhibitor of NTRK, it also targets additional kinases such as the TAM receptors (AXL, MERTK, and TYRO3), and MKNK1 and MKNK2, which may also contribute to anti-tumor growth." (PMID 30885237, 2019). "Of the 46 EGFR-mutated NSCLC tumor specimens for the first- and second-generation EGFR-TKIs, high, intermediate, low, and no AXL expression was observed in 12 (26.1%), eight (17.4%), 23 (50.0%), and three (6.5%) specimens, respectively." (PMID 30651547, 2019). "Although, under hypoxic condition, like tumors, hypoxia inhibits down-regulation of AXL by GAS6, consequently, tumor progression toward EMT may occur in cancers." (PMID 31700829, 2019). "In the present study, we measured the plasma concentrations of AXL and its ligand GAS6 to examine whether they might reflect the corresponding expression levels in tumor tissue." (PMID 31419057, 2019). "Measurement of circulating AXL or GAS6 thus does not appear to be a viable alternative to direct determination of their expression levels in tumor tissue, at least for this patient population." (PMID 31419057, 2019). "We further demonstrated the combining YD, an AXL degrader, and EGFR-TKI resulted in overcoming resistance in EGFR-TKIs resistant NSCLC cells also delaying the emergence of resistance in EGFR-TKI sensitive NSCLC cells using tumor xenograft, and PDX model." (PMID 31043587, 2019). "In this study, the expression levels of GAS6, AXL, Cofilin-1, Claudin-1, as genes involved in EMT, and their relationship with clinicopathological features include; age at diagnosis, TNM staging, size and grade of tumor were investigated in EOC patients." (PMID 31700829, 2019). "AXL expression was heterogeneously distributed in the tumor cells, although AXL-expressing and non-AXL-expressing tumors were not morphologically distinct." (PMID 31497246, 2019). "The median PFS of patients with tumor tissue positive or negative for AXL expression before EGFR‐TKI treatment was 14.3 and 11.9 months, respectively, whereas the corresponding values for OS were 40.5 and 32.1 months, respectively." (PMID 31419057, 2019). "Plasma concentrations of AXL and GAS6 do not reflect tumor expression levels, and their measurement is thus not a viable alternative to direct analysis of tumor tissue in EGFR‐mutated NSCLC." (PMID 31419057, 2019). "However, in the same tumor sample with overexpression of GAS6 (as a ligand), the expression of AXL (as a receptor) in stage I, II was lower than its expression in stages III, IV (high stages)." (PMID 31700829, 2019). "In addition, HOTAIR knockdown significantly suppresses tumor growth and ki-67 expression, increases miR-217 levels and decreases the expression of HIF-1α and AXL, inhibiting tumor growth and EMT." (PMID 31072041, 2019). "It is important to point out that while merestinib is a potent inhibitor of NTRK, it also targets additional kinases such as the TAM receptors (AXL, MERTK, and TYRO3), and MKNK1 and MKNK2, which may also contribute to anti-tumor growth." (PMID 29568395, 2018).
tumor (continued). "Because on BRAF inhibitor monotherapy tumour growth had resumed despite ERK being still inhibited, we wanted to see whether these MITF‐high tumours are enriched for AXL‐high cell populations." (PMID 28606996, 2017). "Overall our data lead to a model, whereby in tumours on treatment with BRAF inhibitor‐induced MITF up‐expression in MITF‐high cells increases intra‐tumour EDN1 levels, which can act on MITF‐high (paracrine or autocrine) as well as AXL‐high cells to re‐activate ERK." (PMID 28606996, 2017). "In untreated tumours, AXL expression was detectable in distinct areas, while other areas of the tumour were negative, confirming the idea of AXL heterogeneity in vivo." (PMID 28606996, 2017). "Its exceptional role in GBM was presented in previous studies showing that experimental inhibition of the RTK-AXL pathway with dominant negative-mutant glioma cells of AXL receptor (SF126 AXL-DN) suppresses glioma growth and prolongs survival in orthotopic tumor model in mice." (PMID 26848524, 2016). "As the TAM RTKs are known to negatively regulate inflammatory immune responses, high DN10764 dosing may have targeted both AXL and MERTK, resulting in hyperinflammation in vivo, ultimately contributing to the promotion of tumor progression and metastasis." (PMID 27829217, 2016). "This is consistent with our findings that AXL inhibition decreases tumor growth via inhibition of metastasis rather than by proliferation." (PMID 27764792, 2016). "Additionally, the anti-AXL antibody YW327.6S2 recognizes both human and murine AXL and is thus useful for preclinical evaluation of the effects of AXL inhibition in the tumor microenvironment." (PMID 27834816, 2016). "Finally, we evaluated the correlation between AXL and TAMs, investigating specific mechanisms by which TNBC cells and macrophages cooperate to influence tumor progression and response to therapy." (PMID 28721387, 2016). "AXL was found to be consistently over-expressed in ESCC cells and human tumor samples." (PMID 27172793, 2016). "Gas6 negatively regulates AXL expression levels in general, but not in hypoxic environments such as in a tumor or in bone." (PMID 26762579, 2016). "Immunofluorescence staining of the harvested tumors indicated that hMAb173 effectively degraded AXL in tumor cells (analyzed with a non-competing antibody), reduced tumor cell proliferation (Ki67 staining), and promoted apoptosis (TUNEL)." (PMID 26356563, 2015). "Although the molecular mechanisms critical for pro-tumor activation of SS-TAMs by apoptotic cells require further evaluation, the present work highlights several candidate oncogenic players such as galectin-3 and the TYRO/AXL/MER axis." (PMID 25702581, 2015). "Tumoral stroma and non-tumoral adjacent tissues were AXL negative, 10% of cases had endothelial cells positivity." (PMID 25966280, 2015). "Knockdown via shRNA #2 did not completely eliminate AXL expression in Lipo-863; however, a significant reduction in tumor volume and weight was noted." (PMID 26573603, 2015). "Neither AXL nor GAS6 were associated with age, sex, tumour primary location, tumour depth and presence of distant metastasis at initial diagnosis (p > 0.05; data not shown)." (PMID 25966280, 2015). "In our study, silencing the expression of AXL did not affect cell proliferation or the subcutaneous tumor growth, but resulted in a slight but significant down regulation of cell migration (data not shown)." (PMID 25551830, 2014). "Therefore, the potential for adverse effects for tumor promotion through the use of systemic anticancer therapies targeting AXL might be a concern and this highlights the importance of more thorough understanding of the tissue and cell-type specific functions of AXL." (PMID 25337673, 2014).
tumor (continued). "Cabozantinib has better effects on tumor angiogenesis and survival than those found with combinations of selective inhibitors of MET and VEGF signaling in the same model, suggesting that AXL or other targets (such as RET, KIT and TIE2) contribute to the efficacy of cabozantinib." (PMID 24213559, 2013). "In particular, the genes ADAM9, AXL, and TNFRSF12A may connect directly between mesenchymal tumor cells and stromal cells." (PMID 22570691, 2012). "Our results revealed a regulatory axis by which elevated GAS6 secreted by reactive astrocytes activates the receptor AXL on the surface of BrM-CSCs, which induces the transcription of CD146, highlighting the role of the TME in engaging the mesenchymal transformation of CTCs and tumor angiogenesis." (PMID 41356185, 2026). "The removal of the tumor during the surgery obviously did not influence the AXL serum levels." (PMID 41563267, 2026). "Moreover, combining IDCs with targeted therapies—such as AXL, VEGF, or CD47 inhibitors—could help to remodel the tumor microenvironment, reduce stromal barriers, and improve intratumoral drug penetration." (PMID 40603576, 2025). "The Gas6/AXL pathway regulates angiogenesis, immune-related molecular markers, and the secretion of certain cytokines (MHC-I, PD-L1, IL-4, CCL3-5, and G-CSF) in the tumor microenvironment, and it also regulates the functions of various immune cells (NK, DC, M2, and Treg)." (PMID 40524208, 2025). "Consistent with in vitro experimental results, cotreatment with bevacizumab and ramucirumab drastically diminished tumor angiogenesis, as evidenced by decreased CD31‐positive staining, and suppressed the expression of angiogenesis and drug resistance‐related genes, FGF and YAP/TAZ/AXL." (PMID 40843133, 2025). "Simultaneous inhibition of both AXL and SRC could prevent resistance and control tumor progression." (PMID 39941857, 2025). "Gas6 binds not only to the receptor tyrosine kinase AXL in PDAC cells, activating the Gas6/AXL signaling pathway and promoting epithelial‒mesenchymal transition (EMT), but also to the receptor tyrosine kinase AXL in NK cells, inhibiting immune cell activation and accelerating tumor cell metastasis." (PMID 41281760, 2025). "Thus, we sought to investigate whether the combination of DSP-0509, an AXL inhibitor, and TLR7 agonist induces robust activation of myeloid cells, resulting in a potent anti-tumor response within the tumor microenvironment." (PMID 39346737, 2024). "Tumor-cell AXL-upregulation correlated with distinct oncotypes and microenvironmental immune-profiles that define chemotherapy-induced mechanisms of ICI-resistance, which suggests the combination of AXL inhibitors with current chemoimmunotherapy regimens can benefit NSCLC patients." (PMID 39238637, 2024). "Tumor cell AXL expression was verified by immunostaining, but not in fibroblasts." (PMID 38525245, 2024). "It has been proposed that AXL inhibition can be achieved by blocking TBK1 (TANK binding kinase 1)/NF-κB pathway, a key signal pathway of immune cells, changes the composition of chemokines and cytokines in tumor microenvironment, making tumor sensitive to treatment." (PMID 37328828, 2023). "Notably, overexpression of AXL expression was observed in HCC-tumor-derived endothelial cells (TECs), although not in the tumor cells of HCC patients with portal vein tumor thrombus (PVTT) type of metastases." (PMID 37469409, 2023). "As such, AXL and MERTK inhibitors might induce adverse effects at the systemic level, and physiological effects of the alteration of AXL and MERTK signaling could be highly tissue-specific and depend on tumor microenvironment." (PMID 37469409, 2023). "Therefore, interactions among the tumor, host immune cells, and abnormal physiological factors in the TME may upregulate AXL and Gas6, thus promoting a pro-tumor microenvironment." (PMID 37265798, 2023).